RNVU1-21 (RNA, variant U1 small nuclear 21)
Synonyms: RNU1-122P
Gene: Small nuclear RNA gene on chromosome 1 (148,334,612 to 148,334,767, reverse strand). Ensembl gene ENSG00000202408.
Gene Ontology:
Molecular function: pre-mRNA 5'-splice site binding
Biological process: mRNA 5'-splice site recognition
Cellular component: U1 snRNP
Homologues: Orthologues: chimpanzee U1 (99% identical), macaque U1 (72% identical), rabbit U1 (58% identical), zebrafish U1 (42% identical). Paralogues in human: RNU1-1 (78% identical), RNU1-2 (78% identical), RNU1-27P (78% identical), RNU1-28P (78% identical), RNU1-3 (78% identical), RNU1-4 (78% identical), RNVU1-18 (78% identical), RNVU1-29 (78% identical), RNVU1-31 (78% identical), U1 (78% identical), RNU1-46P (78% identical), RNVU1-28 (78% identical), and 134 more.